CAST (calpastatin )
Diseases named in the same sentence as CAST in open-access papers (continued):
Sharing a sentence is not in itself a finding about the gene and the disease.
injury (3 papers, 2017 to 2023). Damage inflicted on the body as the direct or indirect result of an external force, with or without disruption of structural continuity. "129S1/SvlmJ and WSB/EiJ were less responsive, whereas CAST/EiJ was again resistant to changes in transcript levels induced by FA kidney injury." (PMID 36752209, 2023). "To evaluate whether CAST overexpression would allow for a better and/or faster recovery after brain injury, we performed several cognitive behavioral tests on WT and hCAST mice, on the 3rd (short-term) or 8th (long-term) week after treatment with either KA or SAL." (PMID 28386216, 2017).
ovarian carcinoma (3 papers, 2012 to 2019). A malignant neoplasm originating from the surface ovarian epithelium. "Yet very little information is available regarding the association of calpains and calpastatin expression with clinicopathological factors and prognosis in ovarian cancer." (PMID 30448882, 2019). "In conclusion, both the previous and the current ovarian cancer patient-based studies indicate that calpain-2 expression is adversely associated with overall survival, with calpain-4 and calpastatin expression also negatively associated with overall survival in the current study." (PMID 30448882, 2019). "Calpain-1, calpain-2, calpain-4 and calpastatin expression were evaluated in primary ovarian carcinomas (n = 575) by immunohistochemistry." (PMID 30448882, 2019). "Calpains and calpastatin showed predominant granular/diffuse staining in the cytoplasm of the ovarian cancer cells with heterogeneity between adjacent tumour cells, varying from weak to intense staining." (PMID 30448882, 2019). "Calpain and calpastatin expression varied among ovarian cancer cell lines yet their expression levels were similar between chemo-sensitive cells and resistant counterparts." (PMID 30448882, 2019). "The conventional calpains and calpastatin have been confirmed to play an important role in ovarian cancer; however, the precise mechanisms whereby they exert effects remain to be elucidated." (PMID 30448882, 2019). "Tissue expression of calpastatin, calpain-1 and calpain-2 was assessed in a series of 154 ovarian cancer patients treated with platinum-based chemotherapy." (PMID 22435971, 2012). "The expression levels of calpastatin, calpain-1 and calpain-2 were determined in a cohort of 154 ovarian cancer patients treated with platinum-based adjuvant chemotherapy." (PMID 22435971, 2012). "The expression of calpain-1, calpain-2 and calpastatin were determined using standard immunohistochemistry on a tissue microarray of 154 primary ovarian carcinomas from patients subsequently treated with platinum-based adjuvant chemotherapy." (PMID 22435971, 2012). "No prior studies have investigated the expression of calpastatin, calpain-1 and calpain-2 in ovarian cancer, or have tested their association with response to platinum-based chemotherapy in tissue samples." (PMID 22435971, 2012).
psoriasis (3 papers, 2011 to 2025). An autoimmune condition characterized by red, well-delineated plaques with silvery scales that are usually on the extensor surfaces and scalp. "Concerning miRNAs, it has been identified that hsa-miR-19a-3p has great potential to become a biomarker for psoriasis because it binds to the mRNA of seven genes (CAST, TSC1, SPATA2, ERAP1, TNIP1, ERBB3 and SDC4) thatare associated with psoriasis." (PMID 40725409, 2025). "Rs27524-G (CAST/ERAP1 locus) was associated with “ankylosing spondylitis” (OR = 0.84, p = 5.4 × 10−7), “iridocyclitis” (OR = 0.88, p = 6.9 × 10−8) and “psoriasis” (OR = 0.85, p = 1.6 × 10−6)." (PMID 39006426, 2024). "In particular, we and others have documented the presence of anti-calpastatin (a natural specific inhibitor of calpain) antibodies in RA and psoriasis." (PMID 22046434, 2011). "In addition, autoantibodies against calpastatin, a natural and specific inhibitor of calpain, are widely observed in RA and psoriasis patients, and positivity for anti-calpastatin antibodies is known to correlate with serological markers of the disease activity." (PMID 22046434, 2011).
tauopathy (3 papers, 2023 to 2025). Neurodegenerative disorders involving deposition of abnormal tau protein isoforms (tau proteins) in neurons and glial cells in the brain. "Additionally, this differential susceptibility of PWK and CAST mice to tauopathy implicates them as promising founder strains in future genetic mapping studies." (PMID 37606887, 2023).
type 2 diabetes (3 papers, 2014 to 2022). "In mouse models of type-1 and type-2 diabetes, transgenic over-expression of calpastatin reduces vascular ROS production, inhibits peroxynitrite formation, and attenuates the dysfunction of endothelium-dependent relaxation." (PMID 24886224, 2014). "Similarly, the protective effect of calpastatin over-expression on endothelial function was also observed in a mouse model of type-2 diabetes, db/db mice (data not shown)." (PMID 24886224, 2014).
amyotrophic lateral sclerosis (2 papers, 2021 to 2023). Amyotrophic lateral sclerosis (ALS) is a neurodegenerative disease characterized by progressive muscular paralysis reflecting degeneration of motor neurons in the primary motor cortex, corticospinal tracts, brainstem and spinal cord. "In an Amyotrophic Lateral Sclerosis mouse model, higher CAST expression was associated with neuroprotective effects." (PMID 36855067, 2023).
COVID-19 (2 papers, 2023 to 2024). A disease caused by infection with severe acute respiratory syndrome coronavirus 2. "In particular, our findings highlight the utility of CAST mice as a model for severe COVID-19 that leads to lethality without associated encephalitis." (PMID 39149485, 2024).
diabetes (2 papers, 2014 to 2022). "Concurrent beta cell-specific overexpression of human calpastatin (CAST) (hIAPP:hCAST), which inhibits calpain, delays or prevents diabetes in hIAPP transgenic mice." (PMID 34554282, 2022). "In parallel, diabetes-induced reduction of endothelium-dependent relaxation in aortic ring was reversed by over-expression of calpastatin in mouse models of diabetes." (PMID 24886224, 2014). "Taken together, over-expression of calpastatin reduces endothelium-dependent dysfunction in diabetes." (PMID 24886224, 2014). "To investigate whether the functional improvement by calpain inhibition was mediated through eNOS-derived NO pathway, we induced diabetes in eNOS-KO and eNOS-KO/Tg-CAST mice by STZ injection." (PMID 24886224, 2014).
encephalitis (2 papers, 2023 to 2024). An acute inflammatory process affecting the brain parenchyma. "However, pathology in the CNS of CAST x K18-hACE2 was striking in that microthrombi were evident in capillaries with extensive hemorrhage in the absence of encephalitis." (PMID 37491352, 2023).
essential hypertension (2 papers, 2002 to 2012). Hypertension that presents without an identifiable cause. "In a previous work, two of us (E.L. and L.B.)showed –using the same transgenic mice– that calpastatin overexpression limits hypertension-induced intimal fibrosis in blood vessels via a decrease in inflammatory cell recruitment and secretion of MIP-1." (PMID 22615899, 2012). "It has been reported that the equilibrium between the erythrocyte protease calpain I and its physiological inhibitor calpastatin is disrupted in patients with essential hypertension." (PMID 11836545, 2002). "Protective factors provided by calpastatin against calpain I activity may be diminished in hypertension, which could explain why it has been reported that calpastatin concentration is decreased." (PMID 11836545, 2002). "The protective factor provided by calpastatin against calpain I activity may diminish under hypertension." (PMID 11836545, 2002).
fetal growth restriction (2 papers, 2021 to 2025). A fetus that does not grow beyond the 10th percentile of conventionally accepted weight for gestational age. "While results of desmin and troponin T degradation did not support increased toughness of IUHS loin muscles would owe to differential proteolysis, there is some evidence to suggest intrauterine growth restriction can increase shear force through upregulation of calpastatin." (PMID 33800814, 2021).
Guillain-Barre syndrome (2 papers, 2022). A spectrum of rare post-infectious neuropathies that usually occur in otherwise healthy patients. "Our results suggest that the calpain-calpastatin system could be involved in a wide variety of demyelinating diseases in the PNS, such as CMT1E, the demyelinating form of Guillain-Barré syndrome, and neuropathic pain, among others." (PMID 36499770, 2022).
heart failure (2 papers, 2016 to 2023). Inability of the heart to pump blood at an adequate rate to meet tissue metabolic requirements. "The calpastatin-calpain system has been extensively implicated in cardiac remodeling and heart failure and has been proposed as a potential therapeutic target for heart disease." (PMID 27588447, 2016).
infarction (2 papers, 2015 to 2022). A localised pathological necrosis of tissue resulting from obstruction of the blood supply usually by a thrombus, an embolus, or vascular torsion. "In the present study, we established a transgenic mouse model overexpressing human CAST and provided the experimental evidence that post-infarction myocardial remodeling is associated with up-regulation and activation of calpains and down-regulation of CAST." (PMID 25786109, 2015). "In mice, the restriction of calpain-1 and calpain-2 activities by using a cardiomyocyte-specific deletion of the common subunit Capn4 or by overexpressing calpastatin reduced adverse-post-infarction remodeling and mortality." (PMID 35456920, 2022). "Transgenic over-expression of CAST inhibits calpain activation and attenuates post-infarction myocardial remodeling." (PMID 25786109, 2015). "The present study aimed to investigate the effect of transgenic over-expression of CAST on the post-infarction myocardial remodeling process." (PMID 25786109, 2015). "Collectively, the present study indicates that over-expression of CAST attenuates MI-induced activation of calpains and subsequently ameliorates post-infarction myocardial remodeling." (PMID 25786109, 2015). "Transgenic over-expression of CAST significantly attenuated MI-induced calpains upregulation and activation and blunted post-infarction myocardial remodeling." (PMID 25786109, 2015). "In addition to post-infarction remodeling, the suppression of Capn4 or the constitutive overexpression of calpastatin attenuated cardiomyocyte hypertrophy and cardiac dysfunction induced by chronic angiotensin II treatment." (PMID 35456920, 2022). "However, the role of CAST over-expression in post-infarction myocardial remodeling remains poorly understood." (PMID 25786109, 2015). "Therefore, the present study established transgenic mice ubiquitously over-expressing CAST and used cultured an in vivo model of MI to investigate the role of CAST over-expression in post-infarction myocardial remodeling." (PMID 25786109, 2015). "The present study also suggests that overexpression of CAST via vector delivery system may be a therapeutic strategy for post-infarction remodeling." (PMID 25786109, 2015).
influenza (2 papers, 2016 to 2021). An acute viral infection of the respiratory tract, occurring in isolated cases, in epidemics, or in pandemics; it is caused by serologically different strains of viruses (influenzaviruses) designated A, B, and C, has a 3-day incubation period, and usually lasts for 3 to 10 days. "CAST is uniquely susceptible to infections such as influenza H3N2 and monkeypox virus." (PMID 33567283, 2021). "Thus, we hypothesized that CAST/EiJ may exhibit a specific deficiency in their response to influenza infection." (PMID 26921172, 2016). "Seven genes were specifically not up-regulated in CAST/EiJ after infection which have not been described in the context of the host response to influenza infections, but may be also important host factors for virus defense in humans." (PMID 26921172, 2016).
kidney damage (2 papers, 2016 to 2022). "To identify putative sequence variants that may account for differential susceptibility to nephropathy, we compared the Sub-IV locus sequence between CAST/EiJ and FVB/NJ strains (Genome Build 38.p3)." (PMID 27736906, 2016).
lymphoma (2 papers, 2009 to 2017). A malignant (clonal) proliferation of B- lymphocytes or T- lymphocytes which involves the lymph nodes, bone marrow and/or extranodal sites. "To examine non-telomerase mechanisms for telomere maintenance in mammalian cells, we used primary cells and lymphomas from telomerase-deficient mice (mTR−/− and Eμmyc+mTR−/−) and CAST/EiJ mouse embryonic fibroblast cells." (PMID 19180191, 2009). "We found that late passage CAST/EiJ mouse embryonic fibroblasts (MEFs) and Eμmyc+mTR−/− lymphomas with short telomeres, exhibit telomere maintenance with minimal changes to the overall length distribution." (PMID 19180191, 2009).
melanoma (2 papers, 2013 to 2020). A malignant, usually aggressive tumor composed of atypical, neoplastic melanocytes. "To determine the respective importance of each target, we then overexpressed calpastatin in tumor or host in isolation, by using a melanoma cell line from the same C57BL/6 genetic background than tumor bearing mice." (PMID 23565252, 2013). "Our results highlight some of the mechanisms by which the calpain/calpastatin system controls melanoma growth and metastatic dissemination." (PMID 23565252, 2013). "Since specificity of available calpain inhibitors remains questionable, we compared melanoma progression in wild type (WT) mice and transgenic mice overexpressing calpastatin (CalpTG), which specifically inhibits both conventional isoforms." (PMID 23565252, 2013). "Surprisingly, calpastatin transgene increased melanoma cell migration properties, as evaluated in monolayer repair assay (p = 0.026 at 10 h, n = 6 experiments)." (PMID 23565252, 2013). "Collectively, these data suggest that calpain inhibition by calpastatin overexpression limits melanoma growth, vascularization, and immune cell infiltrate but paradoxically amplifies its dissemination to regional lymph nodes." (PMID 23565252, 2013). "To assess whether calpastatin transgene in melanoma cells affects apoptosis, we measured propidium iodide-annexin V staining by flow cytometry." (PMID 23565252, 2013). "Since calpain inhibition restricted to melanoma cells limits tumor growth but also increase melanoma cell resistance to apoptosis and dissemination toward lymph nodes, we analyzed the effect of calpastatin transgene expression in melanoma cells on mice survival." (PMID 23565252, 2013). "Transfected melanoma cells (Calpast-Mel) expressed the rabbit calpastatin transgene." (PMID 23565252, 2013). "Because calpain activity is regulated through its interaction with calpastatin and not necessarily due to changes in protein levels, we investigated calpain activity from transfected melanoma cells and found that IRAK-M expression increased calpain activity." (PMID 32533049, 2020). "High IRAK-M expression drastically decreased TRAF6 and calpastatin proteins in melanoma cells but did not change the levels in melanocytes." (PMID 32533049, 2020). "However, restoring calpastatin levels prevented IRAK-M–mediated activation of Bax in Malme-3M and SK-MEL-28 melanomas and substantially reduced cleaved Bax levels in C32 cells." (PMID 32533049, 2020).
myocardial infarction (2 papers, 2015 to 2025). Gross necrosis of the myocardium, as a result of interruption of the blood supply to the area, as in coronary thrombosis. "Calpain is activated following myocardial infarction and ablation of calpastatin (CAST), an endogenous inhibitor of calpains, promotes left ventricular remodeling after myocardial infarction (MI)." (PMID 25786109, 2015).
myocardial ischemia (2 papers, 2022 to 2023). A disorder of cardiac function caused by insufficient blood flow to the muscle tissue of the heart. "Calpain inhibition by genetic deletion of Capn4 or calpastatin overexpression prevents the nuclear translocation of the p65 NF-κB subunit and attenuates hypertrophy induced by myocardial ischemia and angiotensin II." (PMID 35456920, 2022). "Transgenic mouse models with an altered calpain/calpastatin system and the use of calpain inhibitors consistently show that calpains play a key or contributory role in the pathology of a variety of cardiac disorders, including platelet aggregation, myocardial ischemia, and HF." (PMID 35456920, 2022).
myocarditis (2 papers, 2022). Myocarditis is a condition that is characterized by inflammation of the heart muscle (myocardium). "To further uncover the mechanism underlying the effects of calpain in CVB3-induced myocarditis, we induced myocarditis in Tg-CAST mice overexpressing the calpain inhibitor calpastatin and their WT littermates by CVB3 injection." (PMID 35997820, 2022).
pancreatic cancer (2 papers, 2012 to 2022). "In summary, this study demonstrates that low expression of calpain-2 is associated with poor survival in pancreatic cancer and low cytoplasmic calpastatin expression is associated with poor survival in cancers of the bile duct and ampulla." (PMID 23140395, 2012). "The results suggest that calpain-2 and calpastatin expression is important in pancreatic cancers, influencing disease progression." (PMID 23140395, 2012). "This study examined the expression of calpain-1 (μ-calpain catalytic subunit), calpain-2 (m-calpain subunit) and calpastatin in cancers of the pancreas, bile duct and ampulla using immunohistochemistry." (PMID 23140395, 2012). "Based on the HPA database, immunohistochemistry suggested that CAST, CCDC6, and ERLIN1 protein expression was lower in normal pancreatic tissues but higher in pancreatic cancer tissues." (PMID 35938160, 2022). "The expression of μ-calpain, m-calpain and calpastatin has not been previously examined in pancreatic, ampullary or bile duct cancers, however, a single nucleotide polymorphism of calpain-10 (CAPN10) has been associated with an increased risk of developing pancreatic cancer in smokers." (PMID 23140395, 2012).
PLACK syndrome (2 papers, 2021 to 2025). "Previously reported variants in CAST associated with PLACK syndrome have been truncating in nature (frameshift, splice-site, and nonsense mutations)." (PMID 41300744, 2025). "In this study, we describe five children in three sibships of an extended consanguineous family with PLACK syndrome caused by a novel homozygous frameshift variant in CAST." (PMID 41300744, 2025). "The diagnosis of PLACK syndrome was confirmed by detecting a novel homozygous frameshifting variant in CAST in the affected children." (PMID 41300744, 2025). "Recently, dilated cardiomyopathy (DCM) has emerged as a potential systemic manifestation of PLACK syndrome, raising concerns about the impact of CAST deficiency on myocardial function." (PMID 41300744, 2025). "One case previously reported as recessive PC has now been identified as PLACK syndrome with a mutation in the CAST gene." (PMID 34724947, 2021). "PLACK syndrome, caused by biallelic loss-of-function (LOF) variants in the CAST gene, is an ultra-rare autosomal recessive disorder characterized by the following defining dermatologic features: peeling skin, leukonychia, acral punctate keratoses, cheilitis, and knuckle pads (PLACK)." (PMID 41300744, 2025).